GDF15 (growth differentiation factor 15)
Diseases named in the same sentence as GDF15 in open-access papers (continued):
Sharing a sentence is not in itself a finding about the gene and the disease.
heart failure (214 papers, 2008 to 2026). Inability of the heart to pump blood at an adequate rate to meet tissue metabolic requirements. "Growth differentiation factor-15 (GDF-15) has emerged as a biomarker associated with advanced disease profiles, poor outcomes and complex underlying pathophysiological processes in heart failure (HF)." (PMID 41901021, 2026). "Elevated circulating levels of GDF-15 have been consistently linked to adverse cardiovascular outcomes, including an increased risk of heart disease, heart failure, and mortality following both ST-segment elevation and non-ST-elevation myocardial infarction." (PMID 41590509, 2026). "Studies have demonstrated that incorporating GDF-15 improves the predictive accuracy of heart failure risk scores, provides better assessments of bleeding risk in atrial fibrillation, and offers additional prognostic insights in coronary and valvular diseases." (PMID 41590509, 2026). "In contrast, GDF-15 appears to reflect mid- to long-term risk, offering sustained prognostic information for up to five years and showing lower sensitivity to heart failure therapies." (PMID 41590509, 2026). "A meta-analysis revealed the correlation between GDF-15 levels and instances of hospitalization due to heart failure (HHF), cardiovascular death, and mortality from all causes." (PMID 39781722, 2025). "GDF-15 levels have also been linked to right ventricular dysfunction, congestion, and cachexia in advanced heart failure, reflecting its association with systemic metabolic stress." (PMID 41157213, 2025). "Growth differentiation factor 15 (GDF-15) is also associated with heart failure, left ventricular injury, and remodelling and has significant prognostic value in acute heart failure." (PMID 40491666, 2025). "Growth differentiation factor-15 (GDF-15), an emerging biomarker associated with chronic inflammation and oxidative stress, shows potential diagnostic and prognostic significance for heart failure with preserved ejection fraction (HFpEF)." (PMID 41180477, 2025). "In particular it has been linked to cardiovascular aging: GDF15 is strongly associated with cardiovascular outcomes, including heart failure, myocardial infarction, and atherosclerosis." (PMID 40295347, 2025). "Elevated GDF-15 levels are associated with increased risk of all-cause mortality and heart failure hospitalisation." (PMID 41180477, 2025). "Growth differentiation factor-15 (GDF-15) is an emerging predictor associated with heart failure and metabolic diseases, which can regulate LV remodeling in the heart." (PMID 40649868, 2025). "Sequential measurements of GDF-15 in patients with acute heart failure revealed that GDF-15 independently and dynamically predicts the risk of an adverse outcome (all-cause mortality and heart failure rehospitalization) during 1 year of follow-up." (PMID 38398274, 2024). "A recent meta-analysis revealed that GDF-15 consistently adds prognostic information for myocardial infarction and stroke, CV death, and heart failure beyond clinical risk factors and cardiac biomarkers of CVDs." (PMID 38255954, 2024). "The increased expression of GDF-15 has been observed during heart failure (HF) and is associated with worse outcomes." (PMID 38475710, 2024). "GDF15 serves as a general biomarker for several diseases, with its serum level being used to predict all-cause mortality in conditions such as heart failure and cancer." (PMID 37093513, 2024). "They found that in patients with atherosclerotic disease, higher GDF-15 levels were significantly and independently associated with increased rate of cardiovascular death, hospitalization for heart failure, and major adverse cardiac events." (PMID 39660078, 2024). "Data from the Framingham Heart study, in which 85 biomarkers were evaluated, showed that GDF-15 was the only marker with a significant association with the three outcome results: atherosclerotic events, heart failure, and mortality." (PMID 39330316, 2024).
heart failure (continued). "In multivariable analysis RDW, NT-proBNP, troponin T, GDF-15, and ST-2 were associated with death or heart failure." (PMID 39157753, 2024). "Growth differentiation factor-15 (GDF-15) is proposed to be strongly associated with several cardiovascular diseases, such as heart failure and atherosclerosis." (PMID 38254638, 2023). "The precise cause of elevated serum GDF-15 in individuals with cardiovascular events is uncertain but possible explanations include heart failure, ischemia–reperfusion and atherosclerosis-induced cardiovascular injury." (PMID 36864452, 2023). "A recent meta-analysis of individual patients showed that GDF-15 demonstrated a strong and consistent independent association with cardiovascular death and heart failure across all presentations of atherosclerotic cardiovascular disease." (PMID 36935492, 2023). "As a marker of inflammation and oxidative stress, GDF-15 has been associated with adverse prognosis in cardiovascular disease, including coronary artery disease, atrial fibrillation and heart failure." (PMID 37106424, 2023). "GDF15 was also shown to be associated with various cardiovascular events in coronary heart diseases, heart failure, and atherosclerosis." (PMID 35012677, 2022). "GDF-15 was also associated with an elevated risk of adverse events in patients suffering from coronary syndrome, chronic kidney disease or heart failure." (PMID 35600479, 2022). "While the association of GDF-15 with lung fibrosis, heart failure, and PAH has previously been established, our results demonstrate a novel association of EFEMP1 with new onset of restrictive lung physiology." (PMID 35390066, 2022). "In the large Valsartan Heart Failure Trial (Val-HeFT, n = 1734), baseline GDF-15 was independently associated with mortality even after adjusting for multiple clinical and biochemical prognostic variables including BNP, hs-CRP, and hs-Troponin." (PMID 34611778, 2022). "Increased plasma levels of GDF-15 are also associated with heart failure (HF), and linked to HF progression, adverse cardiac remodelling, long-term MACEs, serious cardiac arrhythmic events and mortality." (PMID 35219331, 2022). "GDF15 was reported to have an equal diagnostic capability in heart failure with preserved ejection fraction (HFpEF) patients compared with N-terminal pro-brain natriuretic peptide (NT-proBNP)." (PMID 35012677, 2022). "In a cohort of patients with advanced cancer, serum GDF-15 levels were strongly correlated to weight loss, and patients with chronic renal and cardiac failure were also associated with anorexia-cachexia." (PMID 34150865, 2021). "The analysis of more than 100 original studies shows that GDF15 has higher value in predicting all-cause mortality in patients with heart failure than traditional cardiovascular risk factors and biomarkers." (PMID 34566964, 2021). "Recent studies show associations between GDF15, inflammation, and cardiac fibrosis during heart failure and MI." (PMID 34445593, 2021). "At the same time, it has been observed that only GDF-15 serum concentration is associated with development of heart failure." (PMID 35053194, 2021). "Like heart failure and cancer cachexia, it is likely that GDF15 is a pathogenic factor in the anorexia/cachexia syndrome observed in advanced CKD." (PMID 32310257, 2020). "According to Bouabdallaoui N ‘s research baseline GDF-15 and changes of GDF-15 at both 1 month and 8 months were associated with subsequent mortality and CV events in patients with heart failure in the PARADIGM-HF trial." (PMID 32746821, 2020). "Similar associations have been observed in cardiac failure where higher GDF15 serves not only as a biomarker for mortality risk but there is an inverse relationship seen between GDF15 and body mass index (BMI)." (PMID 31853550, 2020). "In patients with heart failure, GDF-15 has added value beyond the traditional risk factors that predict all-cause and vascular mortality." (PMID 33419237, 2020).
heart failure (continued). "A recently published study observed an association of higher GDF-15 concentration with risk for mortality and heart failure in patients with CKD." (PMID 30819257, 2019). "GDF15 is associated with cardiovascular diseases such as heart failure, coronary artery disease, and atrial fibrillation." (PMID 30542297, 2018). "Another study examined GDF15 levels in 14577 patients with stable coronary heart disease and found GDF15 levels to be associated with cardiovascular death, sudden death, heart failure death, cancer death, and hospitalization for heart failure." (PMID 30542297, 2018). "GDF15 was associated with all-cause mortality, incident heart failure, and major cardiovascular events." (PMID 30542297, 2018). "Based on these findings, biomarkers implicated in heart failure (GDF-15 and GPNMB) and stress (BAX and FAS) were discovered." (PMID 28493232, 2017). "First, the specificity of GDF15 for HCC and LC needs to be better investigated to eliminate diagnostic interference by other diseases associated with GDF15 elevation, such as heart failure and especially other cancers." (PMID 25996938, 2015). "Elevated serum MIC-1/GDF15 levels have been linked to anorexia/cachexia associated with cancer, chronic renal and cardiac failure." (PMID 26207898, 2015). "Fourth, no other markers (eg, galectin-3, high sensitivity troponins, growth differentiation factor 15) that have been suggested to be associated with risks of heart failure were available for all patients." (PMID 25347817, 2014). "In recent years, multiple studies demonstrated that GDF-15 levels are associated with the adverse cardiovascular events across a spectrum of CVD conditions including heart failure, chest pain, acute coronary syndrome, stable ischemic heart disease, stroke and atrial fibrillation." (PMID 41590509, 2026). "Notably, GDF-15 upregulation has been associated with several cardiovascular events, such as heart failure, atrial fibrillation, atherosclerosis, coronary artery disease, and stroke." (PMID 41590509, 2026). "Initially recognized as a stress-responsive cytokine, GDF-15 has emerged as a comprehensive marker of cardiovascular risk and disease progression across a wide range of conditions, including heart failure, atherosclerosis, coronary artery disease, atrial fibrillation, and stroke." (PMID 41590509, 2026). "Additionally, GDF-15, insulin-like growth factor-binding protein-7 (IGFBP-7), NT-proBNP, and hsTropT predict heart failure hospitalization, while GDF-15 and IL-6 are associated with major bleeding events." (PMID 40744929, 2025). "Furthermore, higher GDF15 levels are associated with the development of heart failure, acute coronary syndrome, and atrial fibrillation, and also emerged to be predictive of adverse outcomes in patients with cardiovascular disease." (PMID 41303556, 2025). "Higher levels of GDF-15 were associated with an increased risk of cardiovascular death, hospitalizations for heart failure, and worse kidney outcomes according to an analysis in the cohort of patients included in the EMPEROR-Reduced and EMPEROR-Preserved studies (n = 1124)." (PMID 40141732, 2025). "The potential association between elevated GDF15 and cardiac fibrosis during heart failure (HF) and MI, could presumably be via activation of TGF-β1, a potent stimulator of collagen-producing cardiac fibroblasts." (PMID 40565178, 2025). "Additionally, GDF-15 was associated with increased risk of all-cause mortality and heart failure hospitalisation, with pooled hazard ratios (HR) of 1.46 (95% CI [1.30–1.62]; p < 0.01) and 1.76 (95% CI [1.30–2.38]; p < 0.01), respectively." (PMID 41180477, 2025). "Thus, GDF15 elevation in adults with CKD was first associated with an increased rate of heart failure and higher overall mortality rate, and then the connection with CKD progression was revealed." (PMID 40076962, 2025). "RDW, NT-proBNP, and GDF-15 are associated with all-cause mortality and heart failure." (PMID 39157753, 2024).
heart failure (continued). "Furthermore, a very interesting meta-analysis reports that GDF-15 is consistently useful for prognostic prediction of the risk of cardiovascular death and hospitalization for heart failure among different types of atherosclerotic cardiovascular diseases." (PMID 38828460, 2024). "Additionally, higher levels of GDF-15 are independently associated with cardiac remodeling and poor prognosis in heart failure and atrial fibrillation." (PMID 39335666, 2024). "Therefore, GDF-15 is recognized as a biomarker with strong predictive value for prognosis and all-cause mortality for patients with ischemic heart disease or heart failure." (PMID 38255650, 2023). "In addition, the risk stratification potential of GDF15 in patients with heart failure is currently gaining attention." (PMID 38062533, 2023). "In line with this, an increase in circulating GDF-15 protein was recently associated with an elevated risk of adverse events in patients suffering from acute coronary syndrome, chronic kidney disease or heart failure." (PMID 35600479, 2022). "GDF15 level predicted all-cause mortality in patients with heart failure." (PMID 35012677, 2022). "Moreover, a ROC analysis was performed and AUC was calculated for GDF-15 and sST-2 levels as differential diagnostic indicators for patients presenting with de novo heart failure in the case of either TTC, ICMP or DCMP." (PMID 34805296, 2021). "Finally, analysis of mRNA expression in hearts from Akita mice showed an upregulation in expression of a number of genes associated with heart failure, including Nppa, Nppb, Gdf15, Fgf21 and Myh7." (PMID 32979176, 2020). "In a recent study of three biomarkers: Galectin 3, sSt2 and GDF-15 in adult CKD patients, higher circulating concentrations of all of them were associated with higher mortality, but only elevated GDF-15 concentrations were associated with an increased incidence of heart failure." (PMID 32899694, 2020). "Moreover, in patients with ambulatory heart failure and reduced ejection fraction, GDF-15 is strongly associated with mortality and adverse cardiovascular outcomes." (PMID 32746821, 2020). "Elevated GDF15 levels were associated with increased right atrial and pulmonary capillary wedge pressure and were an independent predictor of adverse outcomes, and with a higher rate of mortality, transplantation, and heart failure." (PMID 33344478, 2020). "While clinical investigations demonstrate GDF-15 as a parameter for risk stratification in myocardial infarction and heart failure, experimental studies show a cardio-protective effect in ischemia and reperfusion;furthermore, GDF-15 is correlated with systemic inflammation." (PMID 23800095, 2013). "In addition to MetSyn, plasma GDF15 may also be a biomarker of pulmonary hypertension and heart failure risk in PLWH with low‐level viremia." (PMID 35510313, 2022). "Indeed, GDF-15 has been previously associated with heart remodeling and heart failure." (PMID 34975851, 2021). "The most notable associations included NT-proBNP for atrial fibrillation (P = 6.31 × 10-313), followed by NPPB (P = 1.03 × 10-164) and GDF15 for heart failure (P = 1.21 × 10-166)." (PMID 40927895, 2026). "In fact, experimental data demonstrated how GDF-15 is able to activate the Smad 2/3 and the Smad 1/5/8 signaling pathways in cultured cardiomyocytes, reducing hypertrophy and apoptosis during heart failure." (PMID 41590509, 2026). "GDF-15 has been investigated as a predictive biomarker in various medical conditions, such as ischemic heart disease, heart failure (HF), atrial fibrillation, diabetes mellitus, and cancer." (PMID 39860501, 2025). "In light chain amyloidosis, a raised level of GDF-15 predicts early death in heart failure and renal disease patients." (PMID 39781722, 2025). "For heart failure hospitalization, 4 biomarkers - GDF-15, IGFBP-7, NT-proBNP and hsTropT - were significantly associated with the outcome, with NT-proBNP and GDF-15 being among the most important risk predictors." (PMID 40744929, 2025).
heart failure (continued). "The cardioprotective effects of empagliflozin on heart failure are more pronounced in patients with higher baseline levels of GDF15." (PMID 40837873, 2025). "Gdf15, a cytokine elevated in ischemic heart disease and heart failure, was significantly upregulated, highlighting the activation of inflammatory and metabolic stress pathways." (PMID 40849623, 2025). "GDF-15 is representative of a multivalent biomarker involved in inflammation, heart failure, and renal dysfunction." (PMID 40428204, 2025). "GDF-15 is increasingly recognized as an important biomarker in cardiovascular diseases, including heart failure, coronary artery disease, and aortic stenosis." (PMID 40430015, 2025). "The conclusion drawn was that GDF-15 played a significant role in evaluating mortality from heart disease, and C reactive protein was identified as a predictor for heart failure." (PMID 39781722, 2025). "Five biomarkers, GDF15, IL6, MMP1, MMP7, and TNFR2, were significantly associated with all 6 non-cancer aging-related conditions, mortality, mobility limitation, heart failure, coronary heart disease, stroke, and dementia." (PMID 39695064, 2025). "Surprisingly, as in the case of GDF15, neopterin has been used rather for the prediction of disease severity and outcome in heart failure patients." (PMID 40076962, 2025). "GDF-15, a cytokine associated with inflammation and cellular stress and linked to frailty, cognitive decline, and cardiovascular disease, when incorporated into aging panels could provide valuable insights into overall health status and predict adverse outcomes like heart failure or mortality." (PMID 40272732, 2025). "It was further demonstrated that in heart failure (HF) patients with preserved ejection fraction (EF) and mildly reduced EF, GDF-15 was independent and superior to BNP in assessing the prognosis." (PMID 39781722, 2025). "Two studies compared children with both congenital heart disease (CHD) and heart failure (HF) to healthy children and found higher GDF15 levels in severe HF compared to mild HF and healthy controls." (PMID 40019842, 2025). "They concluded GDF-15 played a significant role in evaluating mortality from heart disease, and C reactive protein was identified as a predictor for heart failure." (PMID 39781722, 2025). "In healthy human cardiovascular systems, GDF15 maintains basal expression but shows marked elevation during cardiovascular pathologies such as pressure overload, heart failure, ischemia–reperfusion injury, and atherosclerosis." (PMID 40837873, 2025). "GDF-15 is inhibited by visugromab and ponsegromab which are evaluated in clinical phase oncological trials and ponsegromab for heart failure." (PMID 41266767, 2025). "GDF15 expression also increases rapidly with cardiovascular injuries, such as myocardial ischaemia/reperfusion, dilated cardiomyopathy, and heart failure." (PMID 37093513, 2024). "Using a cohort of patients with heart failure, we showed that GDF15 measured in plasma correlated with surrogate markers in urine for protein intake and muscle mass." (PMID 39312445, 2024). "We provide evidence that the blockade of GDF15 activity prevents cachexia and slows the progression of heart failure." (PMID 39312445, 2024). "Novel biomarkers, including high-sensitivity troponins, growth differentiation factor-15 (GDF-15), and soluble suppression of tumorigenesis-2 (sST2), have emerged as potential early indicators of increased heart failure risk." (PMID 39835075, 2024). "The biomarkers MMP-2, TIMP-1, GDF-15, and OPN were particularly notable for their strong associations with adverse clinical outcomes, including heart failure events and all-cause mortality." (PMID 39334904, 2024). "GDF-15 is considered a stress-responsive cytokine that is upregulated in the heart during injury or cardiovascular stress, such as heart failure, myocardial infarction, or pressure overload." (PMID 39768671, 2024).